GAS6 (growth arrest specific 6)
Diseases named in the same sentence as GAS6 in open-access papers (continued):
Sharing a sentence is not in itself a finding about the gene and the disease.
cognitive decline (7 papers, 2021 to 2025). "The vitamin also plays a role in neurological health by activating Gas6 protein, supporting neuron survival and myelination, and potentially protecting against cognitive decline and neurodegenerative diseases." (PMID 40718363, 2025). "VK is also involved in brain health and may help mitigate cognitive decline by carboxylating the Gas6 protein, VKDP, which could protect against neuronal apoptosis induced by oxidative stress and amyloid beta." (PMID 39770962, 2024). "VK is involved in the brain’s physiology and can reduce its cognitive decline by carboxylation of Gas6 protein, a VKDP that could defend against neuronal apoptosis induced by OS and Aβ." (PMID 33917442, 2021). "This preliminary finding encourages further explorations into the interaction of the Gas6/TAM receptor system and cognitive decline in MS." (PMID 39673059, 2024). "Similarly, higher levels of AXL, MERTK, GAS6, LPL, CST7 and CSF1 predicted slower tau accumulation and/or cognitive decline in the A+T+ group." (PMID 37118533, 2022). "Moreover, at an uncorrected level, GAS6 (t = 2.2, P = 0.030) and CSF1 (t = 2.3, P = 0.021) also predicted lower cognitive decline." (PMID 37118533, 2022).
colorectal cancer (7 papers, 2015 to 2025). A primary or metastatic malignant neoplasm that affects the colon or rectum. "This is further supported by recent studies that show increased susceptibility of Axl−/− Mer−/− mice and Gas6−/− mice to azoxymethane/dextran sulfate sodium-induced colitis-associated colorectal cancer compared to WT mice." (PMID 28423548, 2017). "As many patients with advanced colorectal cancer are treated with a 5-FU containing chemotherapy regimen, we assessed the influence of 5-FU on the expression of Gas6 and its receptors in CRC tumor cells and macrophages." (PMID 27486820, 2016). "As we observed expression of Gas6 and its receptors in human colorectal cancer samples, we proceeded to analyze the possible cellular origin." (PMID 27486820, 2016). "As Gas6 has been shown to induce proliferation in different cell types we assessed if Gas6 is also mitogenic for human colorectal cancer cells." (PMID 27486820, 2016). "In order to further understand the possible role of Gas6 in human colorectal cancer, we next analyzed the expression of its receptors in tumor cells." (PMID 27486820, 2016). "Collectively, these data suggest a potential role for Gas6/TAM receptor (especially Tyro3) signaling in colorectal cancer and metastasis progression." (PMID 27486820, 2016). "For example, EVs derived from colorectal cancer perivascular cells contained growth arrest specific 6 (Gas6) and promoted the recruitment of endothelial progenitor cells (EPCs) to tumors by activating the Axl pathway, thus leading to tumor revascularization after withdrawal of antiangiogenic drugs." (PMID 34966744, 2021). "Altogether, our results show that in human colorectal cancer Gas6 is expressed in tumor cells." (PMID 27486820, 2016). "To determine whether Gas6 is likewise expressed in macrophages within human colorectal cancer tissue, we performed stainings and double immunostainings for Gas6 and the macrophage marker CD68, revealing Gas6 expression in a subpopulation of macrophages." (PMID 27486820, 2016). "Furthermore, in human and mouse colorectal cancer Gas6 is even higher expressed in a subset of tumor infiltrating macrophages." (PMID 27486820, 2016). "Thus, we first performed a qPCR analysis for Gas6 in HCT116, SW480, SW620, HT29, DLD-1 and Colo205 human colorectal cancer cell lines." (PMID 27486820, 2016). "Therefore, our findings indicate that elevated YBX1 protein levels may promote colorectal cancer progression by recognizing and stabilizing oncogenic transcripts such as EREG, MAFG, and GAS6, thereby activating downstream signaling pathways involved in tumorigenesis." (PMID 40819060, 2025).
injury (7 papers, 2016 to 2024). Damage inflicted on the body as the direct or indirect result of an external force, with or without disruption of structural continuity. "Schwann cell activity is also related to the interaction with proregenerative macrophages, which may produce Gas6 in response to remyelinating stimuli; Gas6 loss within monocyte lineage cells negatively affects remyelination after nerve injury." (PMID 31636733, 2019). "We selected the NF-κB signaling pathway as the potential anti-inflammatory mechanism of Gas6 on LPS / D-GalN-induced acute liver injury." (PMID 32294688, 2020). "Our present in vivo results suggest the possibility that Gas6/Mer signaling-induced LXRα/Arg2 pathway during LPS-induced acute lung injury leads to downregulated NO production, which in part contributes to the resolution of acute lung injury." (PMID 27406916, 2016). "Our data suggest the possibility that the Gas6-Mer-PI3K/Akt-STAT1-LXR-Arg2 pathway plays an essential role for resolving inflammatory response in acute lung injury." (PMID 27406916, 2016). "Although the cellular origin of GAS6 in the blood of cirrhotic patients is unknown, a rat model of carbon tetrachloride (CCl4)-induced liver injury showed increased expression of GAS6 by aHSCs." (PMID 37004869, 2023).
lung adenocarcinoma (7 papers, 2013 to 2022). A carcinoma that arises from the lung and is characterized by the presence of malignant glandular epithelial cells. "In lung adenocarcinoma, Axl and Gas6 expression levels were associated with tumor advancement and patient survival, thus rendering them as reliable biomarkers and potential targets for treatment of lung adenocarcinoma." (PMID 23242819, 2013). "We recently reported the prognostic significance of the co-expression of AXL and its ligand, GAS6, in lung adenocarcinoma." (PMID 29930762, 2018). "In conclusion, we found that Axl and Gas6 were highly expressed in surgically treated lung adenocarcinoma tissues at both genetic and protein levels, revealing their marked correlations with clinical outcomes." (PMID 23242819, 2013). "In this study, we assessed the clinical involvement of Axl, an RTK, and its ligand, Gas6, in surgically treated lung adenocarcinoma." (PMID 23242819, 2013). "The combination treatment with FO and Se suppresses AXL expression in HCC827 lung adenocarcinoma cells, although few studies show either FO or Se modulates AXL/Gas6 expression in cancer cells." (PMID 36547898, 2022). "Consistent with previous reports, we identified some cell lines that had constitutive Axl activation (i.e. JRMNB) as well as other cell lines that had Gas6-inducible Axl activation, most notably the triple-negative breast adenocarcinoma MDA-MB-231 and the lung adenocarcinoma H1299." (PMID 28272423, 2017).
nephritis (7 papers, 2013 to 2024). Inflammation of renal tissue. "Gas6 is expressed in the mesangial area in animal kidney disease models, such as rat anti-Thy-1 nephritis, anti-GBM nephritis and streptozotocin induced diabetic rat and mouse model." (PMID 23826128, 2013). "Some studies have indicated that specific traits of SLE evaluated in SLEDAI, such as nephritis or neurologic disorder, affect the values of GAS6 or sMerTK." (PMID 23497733, 2013). "In the other 3 cases, Gas6 expression was induced in endothelial and mesangial cells, which was similar to animal nephritis models." (PMID 23826128, 2013). "The establishment of highly sensitive Gas6 ELIZA system can be one of the promising methods to differentiate between nephritis and the other disease, such as bladder infection or urine stone." (PMID 23826128, 2013). "In addition, the bridge protein GAS6 participates in efferocytosis by interacting with the TAM family, while abnormal GAS6 expression is associated with nephritis." (PMID 38779685, 2024). "Of particular relevance for lupus nephritis, Gas6 has been reported to be an autocrine growth factor for mesangial and epithelial cells, and the Axl pathway has been suggested to contribute to nephritis through its essential role in renal mesangial cell proliferation." (PMID 30742665, 2019). "Importantly, other studies of SLE have also shown elevated levels of the ligand Gas6 at active nephritis." (PMID 30742665, 2019).
periodontitis (7 papers, 2018 to 2025). An acute or chronic inflammatory process that affects the tissues that surround and support the teeth. "To study the role of GAS6 under inflammatory conditions, we employed the widely used oral infection model causing murine periodontitis." (PMID 29967614, 2018). "Supporting these findings, AXL, TYRO3, and GAS6 were the most accurate in differentiating between periodontally healthy/gingivitis and periodontitis, including mild or severe periodontitis (area under the curve [AUC] ranging from 0.72 to 0.89)." (PMID 41187004, 2025). "In contrast, a study that investigated age-associated periodontitis of young (2–4 months) versus aged (20–24 months) Gas6−/− mice demonstrated a bone-destructive role for GAS6 in periodontitis." (PMID 38203403, 2023). "In a mouse model of periodontitis induced by P. gingivalis, the loss of MyD88 in TLR signaling significantly reduced the expression of GAS6, AXL, and PROS1." (PMID 34734092, 2021). "In tissues from periodontitis‐compromised patients, gas6 expression levels were decreased, which is incongruent with a previous study." (PMID 32462812, 2020). "The TAM receptors Tyro3, Axl and Mertk and their ligands Gas6 and Pros1 were detected by qRT‐PCR in gingival tissues of patients with chronic periodontitis as well as healthy controls with non‐inflamed gingiva." (PMID 30729671, 2019). "In periodontitis patients, elevated Pros1 and decreased Tyro3 were detected in inflamed gingiva, while the expression of Gas6, Axl and Mertk was similar to that of healthy control." (PMID 30729671, 2019). "While Gas6, Axl and Mertk were detected at similar levels in periodontitis and control gingiva, Pros1 was found to be up‐regulated and Tyro3 down‐regulated in periodontitis specimens compared with controls." (PMID 30729671, 2019). "However, similar levels of AXL and GAS6 have been detected in human gingival tissues with or without chronic periodontitis using qPCR." (PMID 34734092, 2021). "However, the specific roles of GAS6 and AXL in periodontitis remain unclear." (PMID 34734092, 2021).
thyroid cancer (7 papers, 2014 to 2024). "GAS6 was secreted only by thyroid cancer cells (NIM) that were used as a positive control, suggesting a ligand-independent activation of AXL in human CRC cells." (PMID 25966280, 2015). "Thyroid carcinomas induced by exposure to radiation show increased levels of both Gas6 and Axl with reduced apoptosis, implying an autocrine activation of Axl." (PMID 25344858, 2014). "Gas6 mRNA is also expressed in thyroid cancer cells where it has a slight mitogenic effect, and thus is considered a growth factor for Axl-expressing thyroid carcinoma cells." (PMID 25344858, 2014). "Consistently, AXL stimulation with its ligand growth arrest-specific gene 6 (GAS6) increased AKT1- and p65 NF-kB-phosphorylation and promoted survival of thyroid cancer cell lines in culture." (PMID 31181609, 2019). "AXL and its ligand GAS6 mRNA were also screened by real time-PCR (RT-PCR) using TPC1 and CAL62, two thyroid cancer cell lines, as positive controls." (PMID 25966280, 2015). "Notably, these candidate IFT57-dependent genes have reported functions in other cancers, and roles for GAS6 and NID2 have been reported in thyroid cancer." (PMID 39201643, 2024).
type 2 diabetes (7 papers, 2013 to 2017). "Data from recent studies suggest that polymorphisms in the Gas6 gene are associated with cardiovascular disorders and type 2 diabetes (T2D)." (PMID 26284522, 2015). "Additionally, the inverse correlation between plasma Gas6 concentration and proinflammatory cytokines was observed in patients with type 2 diabetes." (PMID 28270700, 2017). "In addition, we evaluated the association between plasma Gas6 protein levels and corresponding glucose values under acute glucose challenge using oral glucose tolerance test (OGTT) in 104 type 2 diabetic patients." (PMID 24572151, 2014).
Venous thrombosis (7 papers, 2015 to 2022). Formation of a blood clot (thrombus) inside a vein, causing the obstruction of blood flow. "In our study, we observed that H1N1 viral infection increases GAS6 expression and higher GAS6 expression is associated with a higher risk of MI which is consistent prior work demonstrating that GAS6 deficient mice are protected from thrombosis." (PMID 26193668, 2015). "For example, mice deficient in Gas6 or TAM receptors or treated with inhibitors of Gas6/TAM receptor pathways develop less arterial and venous thrombosis." (PMID 30980657, 2019). "In a stasis-induced venous thrombosis model Gas6−/− mice developed significantly smaller thrombi than did WT mice." (PMID 29868590, 2018). "Gas6 knockout mice experiments showed that these mice were resistant to venous and arterial thrombosis." (PMID 25805676, 2015). "Gas6 knockout mice studies showed that these mice were resistant to venous and arterial thrombosis and had normal hemostasis parameter values." (PMID 25805676, 2015). "Additionally, gas6 was reported to promote monocyte recruitment in venous thrombosis, gas6 is also expressed in platelets and interacts with endothelial cells, monocytes, and neutrophils." (PMID 32462812, 2020). "Gas6 knockout mice were resistant to venous and arterial thrombosis." (PMID 25805676, 2015). "Inhibition of the Gas6/TAM pathway leads to decreased platelet activation responses in vitro and protects mice from arterial or venous thrombosis in vivo." (PMID 29868590, 2018). "Gas6 can amplify endothelial cell activation through TF expression, collect platelets and leukocytes to the endothelial cell membrane, and promote the recruitment of monocytes through a CCR2/CCL2-dependent mechanism during venous thrombosis." (PMID 35444662, 2022). "Transgenic mice deficient in GAS6, or any of the TAM family of receptors that engage this ligand, exhibit in vivo protection against arterial and venous thrombosis but do not demonstrate either spontaneous or prolonged bleeding compared to their wild-type counterparts." (PMID 29868590, 2018).
acute kidney injury (6 papers, 2013 to 2025). Sudden and sustained deterioration of the kidney function characterized by decreased glomerular filtration rate, increased serum creatinine or oliguria. "Gas6 was found to be detectable in the urine of mice with podocyte proliferation in response to acute kidney injury." (PMID 30934817, 2019). "Recombinant mouse Gas6 reduced vascular calcification in rats and showed improvement of acute kidney injury with increased survival rate in septic mice." (PMID 30934817, 2019). "Patients with renal failure (n = 5) presented higher values of GAS6 (42.5 ± 4.0 ng/mL vs 31.2 ± 1.5 ng/mL; P = 0.023); MerTK (31.4 ± 7.3 ng/mL vs 20.1 ± 1.4 ng/mL; P = 0.024); and Tyro3 (4.6 ± 0.4 ng/mL vs 3.5 ± 0.2 ng/mL; P = 0.031)." (PMID 23497733, 2013). "In addition, Gas6 was detected in the urine of mice with podocyte proliferation in response to acute kidney injury." (PMID 30934817, 2019). "We confirmed higher values of both GAS6 and sMerTK in patients with renal failure." (PMID 23497733, 2013). "Poricoic acid also protects the kidneys during the progression of Acute Kidney Injury (AKI) to CKD by regulating the Gas6/AxlNFkB/Nrf2 pathway." (PMID 35673387, 2022).
diabetes (6 papers, 2013 to 2025). "The axis has been described as an important pathogenic mechanism for cardiovascular and renal complications associated with diabetes, and GAS6 is dysregulated in type 2 diabetes (T2D)." (PMID 37778719, 2023). "We thus found four hub genes (App, F5, Fgg, and Gas6) that were closely related to vascular regulation and diabetes." (PMID 34531764, 2021). "GAS6 functions as a pleiotropic molecule involved in multiple disease processes, playing a crucial role in the onset and progression of cardiovascular diseases, cancer, and diabetes." (PMID 40872581, 2025).
glomerulonephritis (6 papers, 2013 to 2025). A renal disorder characterized by damage in the glomeruli. "Gas6 is a growth factor that causes proliferation of mesangial cells in the development of glomerulonephritis." (PMID 23826128, 2013). "Gas6 is a growth factor expressed in endothelial/mesangial cells with its receptor, Axl, which causes proliferation of mesangial cells in rat glomerulonephritis model." (PMID 23826128, 2013). "The importance of Gas6/Axl pathway in renal inflammation has been demonstrated by several animal models of glomerulonephritis with genetic disruption of Gas6 and Axl, and small molecule inhibitor targeted therapy." (PMID 35740998, 2022). "Previous studies have suggested that Axl and Gas6 have critical roles in the development of glomerulonephritis." (PMID 30742665, 2019). "Gas6 was reported to be involved in the progression of glomerulonephritis and the development of diabetic nephropathy." (PMID 23826128, 2013). "Although this suggests that AXL and Gas6 strongly contribute to disease progression of glomerular nephritis, the precise mechanism of AXL in kidney diseases remains unknown." (PMID 32324796, 2020). "In the cases with endo/mes type, according to a previous report, the role of Gas6 could be an exacerbation factor for glomerulonephritis through mesangial proliferation, and Axl was the receptor for Gas6." (PMID 23826128, 2013).
renal cell carcinoma (6 papers, 2015 to 2022). "Moreover, Axl is known to be involved in the integrity of the vasculature; a study indicated a role for Gas6/Axl signaling in promoting the angiogenic potential of renal cell carcinoma cells." (PMID 34326776, 2021). "In a model of renal cell carcinoma, Gas6/Axl signaling induces metastasis formation through a crosstalk with src kinase and RTK Met, indicating that the molecular requirements necessary for Axl activation may be tumor-specific." (PMID 26356564, 2015). "Also, in renal cell carcinoma (RCC), Gas6 expression is found." (PMID 35760058, 2022). "The prognostic value of Gas6 in renal cell carcinoma (RCC), especially in non-clear cell RCC, is still unclear." (PMID 35760058, 2022). "These biomarkers were selected based on biological relevance to renal cell carcinoma, previous reports of prognostic significance, and the target profile of cabozantinib including both cabozantinib receptor targets (VEGFR2, MET, and AXL) and their ligands (VEGF, HGF, and GAS6)." (PMID 34364385, 2021).
rheumatoid arthritis (6 papers, 2010 to 2023). A chronic, systemic autoimmune disorder characterized by inflammation in the synovial membranes and articular surfaces. "TAM receptors and Gas6 have been described as being expressed in synovial tissue of rheumatoid arthritis (RA) patients, in which Gas6 levels were lower in erosive RA compared with non-erosive RA." (PMID 37242486, 2023). "In contrast, a reduction of splenic T-helper 1 cell was observed in an animal model of rheumatoid arthritis after Gas6 overexpression, and the mechanism needs to be further investigated." (PMID 28270700, 2017). "Furthermore, Gas6 might be involved in other chronic systemic autoimmune diseases, such as rheumatoid arthritis and chronic inflammatory demyelinating polyneuropathy." (PMID 20637106, 2010).
acute coronary syndrome (5 papers, 2013 to 2025). Signs and symptoms related to acute ischemia of the myocardium secondary to coronary artery disease. "We then investigated the association between GAS6 levels and coronary collateral formation and the risk of MACEs in patients with acute coronary syndrome (ACS) and a previous MI." (PMID 39195894, 2024). "To investigate the dynamics of the two distinct forms of sAXL in CVD, we analyzed the levels of sAXL and the Gas6/AXL complex in patients with acute coronary syndrome (ACS)." (PMID 40933570, 2025).